APLN (apelin)
Diseases named in the same sentence as APLN in open-access papers (continued):
Sharing a sentence is not in itself a finding about the gene and the disease.
Obesity (continued). "Regular aerobic and resistance exercise training was correlated with a decrease in apelin concentration and a positive change in body composition such as body fat and WC, thereby lowering the risk of cardiovascular disease and metabolic syndrome as well as obesity." (PMID 30696454, 2019). "However, obesity has to be associated with hyperinsulinemia, so it may be the main cause for the rise in the expression of apelin." (PMID 29977292, 2018). "Therefore, the purpose of the present study was to investigate possible correlations between apelin-12 levels and obesity in children in China and identify associations between apelin-12 and obesity-related markers, including lipids, insulin sensitivity and insulin resistance index." (PMID 24475149, 2014). "Obesity leads to reduced secretion of anti-inflammatory adipokines (such as adiponectin and apelin) and cytokines (like IL-10)." (PMID 41562846, 2026). "GDM and obesity are multifactorial conditions influenced by various biochemical and molecular factors, such as apelin, VEGF, leptin, and DNA methylation." (PMID 41302116, 2025). "In contrast, obesity-induced insulin resistance is likely to be responsible for the marked increase in apelin levels in obese individuals." (PMID 40414892, 2025). "Emerging research has confirmed that obesity-induced increases in apelin expression contribute to the progression of BC." (PMID 40414892, 2025). "For example, Apelin induces browning of white adipose tissue by increasing thermogenesis and promoting metabolic health, which is important for prevention of obesity and metabolic syndrome." (PMID 41278731, 2025). "Apelin expression was increased in numerous pathological conditions in the human body, including obesity, diabetes, and cancers." (PMID 40076482, 2025). "Although depression and obesity share a myriad of biological mechanisms, studies exploring apelin levels in depression have been inconclusive so far." (PMID 41375608, 2025). "Previous scientific research has proved increased expression of circulating adipokines, including leptin and apelin, in patients with obesity-related cancers such as breast cancer and prostate cancer." (PMID 40076482, 2025). "In contrast, adipose tissue APLN expression is increased in people with T2D, suggesting that adipose tissue is responsible for increased circulating APLN levels in obesity and T2D." (PMID 40171198, 2025). "Apelin secretion is insulin-dependent, therefore its levels tend to soar in obesity and hyperinsulinemia." (PMID 41375608, 2025). "Previous scientific research has shown an increased expression of circulating adipokines—leptin and apelin—in obesity-related cancers such as breast cancer and prostate cancer." (PMID 40076482, 2025). "The important role of apelin in various pathological conditions (e.g., diabetes, obesity, cardiovascular disease, and PCOS) has been demonstrated." (PMID 41302116, 2025). "In this review, we show, in an updated way, the link between obesity and changes in the signaling pathways of the adipokines leptin, adiponectin, resistin, visfatin, apelin, chemerin, omentin‐1, vaspin, and asprosin in male reproduction." (PMID 40195898, 2025). "Elevated apelin levels are commonly observed in women with PCOS, especially those with obesity, and are associated with insulin resistance and metabolic disturbances." (PMID 40911578, 2025). "The administration of apelin improves insulin sensitivity in obesity and diseases related to insulin resistance." (PMID 39457235, 2024). "A similar safety profile was also reported for the G-protein biassed agonist MM07 and the small molecule agonist as well as for [Pyr1] apelin in obesity and patients with heart failure." (PMID 38803685, 2024). "In women with PCOS, chemerin, lipocalin, and apelin concentrations were influenced by overweight and obesity status, with the highest concentrations observed in those with a body mass index (BMI) ≥ 30.0." (PMID 39201400, 2024).
Obesity (continued). "Plasma apelin concentration has been well-documented to increase in individuals with obesity and type 2 diabetes (Singla, Bardoloi & Parkash, 2010)." (PMID 39465147, 2024). "Other adipokines including apelin and chemerin, which are overexpressed in obesity, exhibit oncogenic properties." (PMID 38255203, 2024). "Apelin concentrations are increased in patients with obesity, impaired glucose tolerance and diabetes mellitus type 2 (DM2)." (PMID 39519480, 2024). "Obesity increases the levels of Apelin, an evolutionarily conserved peptide that acts through the G protein-coupled Apelin receptor (APLNR)." (PMID 39040042, 2024). "Consistent with its supposed role as an adipokine, high plasma apelin has been indicated by several studies in severe obesity and correlated with body composition." (PMID 37930396, 2024). "Since serum levels of apelin are elevated in diabetes and/or obesity, it is possible that such systemic diseases promote the development and progression of periodontitis via apelin." (PMID 39189510, 2024). "APLN levels are higher in obesity but drop with weight loss, while IRSN decreases in obesity but increases during exercise." (PMID 39109340, 2024). "Apelin is also involved in pathological conditions such as diabetes, obesity, heart failure, and cancer." (PMID 39457235, 2024). "On the other hand, there are studies that demonstrated negative correlations of apelin with HOMA indices and insulin concentrations, while apelin concentrations were lower in subjects with obesity, although the sample size was very small." (PMID 39519480, 2024). "Apelin, vaspin and resistin are adipokines that play a crucial role in the pathophysiology of obesity." (PMID 39519480, 2024). "The present study expands the understanding that MSCs, particularly those overexpressing apelin, have a profound impact on diabetes and obesity management." (PMID 38622732, 2024). "Since the serum levels of apelin are elevated in diabetes and/or obesity, it is possible that these systemic diseases promote the development and progression of periodontitis via apelin." (PMID 39189510, 2024). "In fact, elevated concentrations of apelin correlate with metabolic alterations in lipid and glucose metabolism of mouse and human adipocytes, degenerating in obesity and diabetes." (PMID 38731880, 2024). "Apelin promotes biogenesis and mitochondria function in obesity-related sarcopenia and plays a role in the treatment of obesity." (PMID 39590824, 2024). "Elevated apelin concentrations in human serum have also been found in obesity, but normalized with dietary changes and calorie reduction." (PMID 39189510, 2024). "Apelin is another exercise-induced myokine and improves the muscle cell metabolism and contributes to a beneficial metabolic effect in obesity." (PMID 39590824, 2024). "It therefore seems likely that the metabolic effects induced by elevated plasma apelin concentrations in metabolic diseases such as obesity and T2DM are, at least initially, part of a compensatory mechanism to maintain functions such as insulin sensitivity." (PMID 39189510, 2024). "It has been shown that apelin levels are increased in systemic diseases and conditions such as obesity and diabetes." (PMID 36902162, 2023). "Apelin is abundantly secreted by adipocytes, and plasma apelin concentrations are elevated in patients with obesity and T2DM." (PMID 38074873, 2023). "Animal studies have revealed exciting development in the treatment of obesity and diabetes using apelin analogs." (PMID 36831180, 2023). "The rs2281068 variant (APLN gene) is associated with T2DM in the Chinese Han population, whereas the rs3115757 variant correlates with obesity among women in a Chinese population." (PMID 36983642, 2023). "A similar increase in TM4SF5 and apelin levels during obesity or NAFLD development was also found in a public dataset of GSE48325." (PMID 37670786, 2023).
Obesity (continued). "Studies focusing on the regulatory effects of Apelin-13 on obesity are relatively limited, and the molecular mechanisms underlying this process require further exploration." (PMID 38089606, 2023). "In several study cohorts, serum apelin levels were elevated in obesity, hypertension, and type 1 and type 2 diabetes." (PMID 37238973, 2023). "Our study evaluated the data of obese T2DM patients and healthy volunteers with lean T2DM patients to investigate the role of Apelin and obesity in contributing to the development of IR, CAD, and impaired glycemia." (PMID 37706122, 2023). "Apelin is also involved in glucose homeostasis, and higher levels of apelin were observed in obesity and T2DM." (PMID 38203346, 2023). "Higher plasma concentrations of apelin correlated with hyperinsulinemia were observed in animal models of obesity." (PMID 38203346, 2023). "Generally, Apelin-13 mainly improves obesity by inhibiting adipocyte differentiation、 promoting fat decomposition and cell apoptosis." (PMID 38089606, 2023). "Apelin, which is an adipokine secreted by adipose and other tissues, shows elevated expression in obesity; it plays a central key role in lipid and glucose metabolism and is also implicated in atherosclerosis and oxidative stress." (PMID 37176607, 2023). "With regard to obesity, some studies have shown that circulating apelin levels are higher in individuals with obesity, especially those with diabetic comorbidities." (PMID 36750692, 2023). "Apelin improves glucose and fatty acid metabolism, and protects from obesity, hypertension and cardiovascular diseases." (PMID 37238973, 2023). "Apelin is expressed in several pathophysiological conditions such as osteoarthritis, obesity, diabetes mellitus, and diabetes-related diseases." (PMID 37654901, 2023). "Yet, another study did not confirm these implications and rather documented reduced apelin levels in obesity and metabolic diseases." (PMID 37238973, 2023). "These contrasting results suggest that other factors, such as insulin levels, rather than adiposity itself, determine the circulating levels of apelin in obesity." (PMID 36750692, 2023). "On the other hand, the correlation between apelin mRNA levels and markers of hepatic oxidative stress highlighted a possible role of the apelinergic system in obesity-induced liver oxidative steatosis and dysfunction." (PMID 36902176, 2023). "This review outlined the physiological effects of the apelinergic system, the relationship between apelin and metabolic disorders such as diabetes and obesity, as well as the effect of apelin on the reproductive system in both gender." (PMID 37424869, 2023). "Stable apelin-13 peptide analogues have shown promising short-term antidiabetic effects in mice with diet-induced obesity and diabetes." (PMID 35355561, 2022). "After obesity adjustment multivariate logistic regression showed that the apelin to NT-proBNP ratio < 0.82 × 10−2 units remained the only independent predictor for HFpEF (OR = 1.44; 95% CI: 1.18–2.77; p = 0.001) HFpEF in T2DM patients." (PMID 35050233, 2022). "It seems that increased apelin with exercise can be used as a new therapeutic target for obesity and metabolic diseases." (PMID 36093083, 2022). "After obesity adjustment, multivariate logistic regression showed that the apelin to NT-proBNP ratio < 0.82 × 10−2 units remained sole independent predictor for HFpEF (OR = 1.44; 95% CI: 1.18–2.77; p = 0.001) HFpEF in T2DM patients." (PMID 35050233, 2022). "This study was conducted to investigate the role of exercise and apelin during pregnancy and also to find effective mechanisms for pregnancy complications such as obesity, gestational diabetes, preeclampsia, and cardiac hypertrophy." (PMID 36093083, 2022). "In clinical and experimental studies, serum apelin level or its adipose tissue expression is increased in obesity and insulin resistance status." (PMID 35355561, 2022).
Obesity (continued). "Understanding the regulation of apelin secretion is key as it plays a pivotal role in obesity, diabetes, cancer, heart failure, increasing cardiac output, and hypoxia-related diseases attenuating oxidative stress." (PMID 36187132, 2022). "While maternal and neonatal apelin secretion is reduced in obesity and insulin-resistant obesity compared with controls." (PMID 36093083, 2022). "Apelin plays a central role in insulin resistance, glucose metabolism, obesity-related inflammation, water homeostasis and osmotic regulation in T2DM." (PMID 35050233, 2022). "Apelin levels probably increase during obesity to compensate for a state of insulin resistance, hyperinsulinemia, and impaired glucose metabolism." (PMID 35628332, 2022). "We found lower apelin and nitric oxide levels in patients with hypertension and obesity and in their COVID-19-infected counterparts." (PMID 36352477, 2022). "Overview of longer-term beneficial effects of various apelin-13 analogues in rodent models of obesity-diabetes." (PMID 35177945, 2022). "Generally, apelin as an exercise-induced factor has an anti-sarcopenic obesity function by targeting satellite cells and fat cells." (PMID 35250869, 2022). "Apelin as an exerkine reverses obesity-related placental dysfunction by increasing mitochondrial biogenesis in mice." (PMID 36093083, 2022). "Previous research has shown apelin contributes to obesity-related disorders other than cancer, particularly those with insulin resistance." (PMID 36230579, 2022). "Although high apelin levels have been found in obesity, clinical studies have reported a wide range of apelin plasma levels in healthy subjects and patients of different pathologies." (PMID 36291097, 2022). "It will be essential to consider confounding factors affecting serum apelin levels in obesity-related cancers to delineate changes in apelin and the underlying mechanisms associated with cancer development and progression." (PMID 36230579, 2022). "Ten years later a putative role for apelin in obesity was described, mainly through the promotion οf angiogenesis in adipose tissue." (PMID 36077676, 2022). "Apelin, a peptide hormone, exerts its effect by binding with angiotensin II protein J receptor (APJ) and is considered to be linked with diabetes and obesity." (PMID 35355561, 2022). "Apelin deficiency mice display increased adiposity and elevated circulating free fatty acids, whereas transgenic mice with over-expressed apelin is resistant to obesity." (PMID 35355561, 2022). "Apelin was, until recently, described as an adipokine whose expression and circulating levels were increased in obesity; further evidence showed that apelin is also produced by myocytes during muscle contraction." (PMID 36359757, 2022). "Recent investigations point out that apelin peptide can be used as a beneficial adipokine in metabolic disorders and a promising therapeutic target for anti-obesity and anti-diabetics." (PMID 35610700, 2022). "An increased plasma concentration of apelin was noticed in animal models of obesity correlated with hyperinsulinemia." (PMID 34212049, 2021). "Apelin is expressed and released from adipose tissues, and its regulation is interrupted in obesity and insulin resistance." (PMID 34660801, 2021). "Apelin also plays an important role in the treatment of carbohydrate disorders such as obesity or type II diabetes." (PMID 35011661, 2021). "Apelin is an adipokine with an intermediatory role in obesity and insulin resistance, which can be modified by dietary intake." (PMID 34660801, 2021). "Several researchers have considered apelin as an adipokine because of its upregulation in adiposity mass with obesity and improvement of cardiometabolic diseases." (PMID 33743591, 2021). "In this study, we analyzed in a retrospective cohort of 62 breast cancer patients the impact of obesity and tumoral apelin expression on response to neoadjuvant chemotherapy." (PMID 33972642, 2021).
Obesity (continued). "Reproducing obesity-related levels of apelin is sufficient to promote BC growth and metastatization." (PMID 33972642, 2021). "At the same time, both in vivo and in vitro experiments confirmed that apelin can increase brown-like characteristics in white adipocytes, which provides a potential therapeutic approach to combat obesity and metabolic disorders." (PMID 33679444, 2021). "This research investigated the symbiotic supplement influences on serum glycemic indices and lipidsas well as apelin rates and obesity values in polycystic ovary syndrome (PCOS) patients." (PMID 33497048, 2021). "Similar to leptin and visfatin, other adipokines overexpressed in obesity, such as resistin, apelin, and chemerin, also possess some oncogenic functions." (PMID 33535537, 2021). "The apelin gene (APLN) is localised on the X chromosome at Xq25-q26.1, a region close to a susceptibility locus for obesity that was identified by linkage mapping in the African Americans, while the apelin receptor gene (APLNR) is located on chromosome 11q12." (PMID 32998691, 2020). "Various studies confirmed that apelin plays a key role in energy metabolism and pathophysiology of obesity." (PMID 33192583, 2020). "Overexpression of apelin also prevents HFD-induced obesity by promoting mitochondrial biogenesis and increasing energy expenditure in skeletal muscle." (PMID 33379163, 2020). "In our experiments, the reproduction of obesity‐related levels of apelin in lean mice led to a marked increase of brain TNBC metastase production." (PMID 32681609, 2020). "Many reports have demonstrated that apelin plays a physiological role in the regulation of glucose homeostasis and obesity." (PMID 33278072, 2020). "In order to discriminate the influence of apelin on tumour growth from obesity‐related protumoral mechanisms, we performed this experiment in ND‐fed obesity‐resistant Balb/cJRj mice injected with 4T1 TNBC." (PMID 32681609, 2020). "For example, various adipocytokines (e.g., adiponectin, apelin, chemerin, leptin) are secreted from adipocytes, but in obesity, the regulation of the production of these adipocytokines is aberrant due to enlarged adipocytes." (PMID 33110098, 2020). "In this study, we showed for the first time that obesity‐increased apelin expression favours breast cancer progression." (PMID 32681609, 2020). "Many cell types, including adipocytes, secrete apelin and its expression is controversially upregulated in obesity." (PMID 33327460, 2020). "We further highlighted that the reproduction of obesity‐related levels of apelin in lean mice led to an increased TNBC growth and brain metastases formation." (PMID 32681609, 2020). "This reduction of TNBC growth occurs without the necessity of targeting obesity confirming a key implication of apelin protumoral effects in the context of obesity." (PMID 32681609, 2020). "Among, relatively, recently identified adipokines, visfatin, chemerin, apelin, and semaphorin 3 C (SEMA3C) are reported to be associated with obesity and T2DM." (PMID 32561824, 2020). "Despite the limited expression of Aplnr and a suggested lack of proliferative effect in 4T1 TNBC cells, the reproduction of obesity‐related levels of apelin was able to promote 4T1 TNBC growth and metastasization." (PMID 32681609, 2020). "The main condition known to modulate circulating apelin levels is the development of obesity that increases apelin expression in adipose tissue." (PMID 32681609, 2020). "First, by accurately mimicking apelin levels as observed in obesity condition, we showed that apelin is sufficient to promote TNBC growth in lean mice and to increase tumour angiogenesis." (PMID 32681609, 2020). "In this study, HF/HC‐fed rats were used for a reasonably long time as models of obesity and diabetes to study the effects of L‐carnitine on the apelin gene expression in AT." (PMID 33278072, 2020).